IL10 (interleukin 10)
Diseases named in the same sentence as IL10 in open-access papers (continued):
Sharing a sentence is not in itself a finding about the gene and the disease.
Insulin resistance (continued). "- ↓ plasma triglycerides, liver lipids, liver triglycerides, insulin resistance, fasting glucose, fasting insulin, thoracic circumference, abdominal circumference, products of lipid oxidation, pro-inflammatory cytokine expression (IL-1β);- ↑ anti-inflammatory cytokine expression (IL-10)." (PMID 33693024, 2021). "An study showed that the anti-inflammatory cytokine (IL-10) serum levels were significantly reduced in subjects with morbid obesity and obstructive sleep apnoea, and reported a strong correlation with a systemic state of hyperinsulinemia and insulin resistance." (PMID 34501884, 2021). "In addition, IL-10 is a typical anti-inflammatory cytokine which could prevent the insulin resistance and MS in mice." (PMID 34574191, 2021). "In conclusion, the present study demonstrated that serum levels of the anti-inflammatory cytokine IL-10 are significantly reduced in morbidly obese subjects with obstructive sleep apnea and show a strong correlation with a systemic state of hyperinsulinemia and insulin resistance." (PMID 25944984, 2015). "Enhancing adipose IL-10 induces Treg expansion, inhibits JNK and NF-κB signaling, and alleviates hepatic gluconeogenesis and insulin resistance." (PMID 41898743, 2026). "Primary outcomes included insulin resistance (HOMA-IR), insulin sensitivity (Matsuda index), mtDNA DAMPs (ND1, ND6), pro/anti-inflammatory cytokines (IFN-γ, IL-10, IL-6, IL-8, TNF-α), CRP, and cortisol." (PMID 41156500, 2025). "This is particularly evident in T1DM, where IL-10 inhibits autoreactive T cells targeting pancreatic β-cell, and in T2DM, where it mitigates inflammation in adipose tissue, alleviating insulin resistance." (PMID 40370441, 2025). "Taken together, these results suggest that the injection of IL-10-treated SVFs enhances Akt and STAT3 activation and attenuates insulin resistance in Leprdb/db mice." (PMID 39125659, 2024). "The results showed that JTP decreased blood glucose (FBG, HbA1c) and blood lipid (TC, TG, and LDL) levels and alleviated insulin resistance (FINS, IL-10) in T2DM rats." (PMID 37229468, 2023). "We demonstrated a significant increase in the IL10 expression level, IL10 promoter region methylation, and histone 3 epigenetic modifications: H3K4me and H3K9/14ac, in insulin resistance cells (IR) from SAT cell culture." (PMID 35205339, 2022). "Despite rare engraftment of UC-MSCs in EAT, UC-MSC infusions attenuated insulin resistance in EAT by polarizing macrophages into the M2 phenotype, coupled with elevated serum IL-10 levels." (PMID 35313972, 2022). "In summary, the anti-IL-10 antibody blunted UC-MSC-induced macrophage polarization and amelioration of insulin resistance in EAT." (PMID 35313972, 2022). "IL-10 increases the glucose uptake, improves the insulin sensitivity and inhibits the TNF-α mediated insulin resistance in adipocytes and skeletal muscle with lowering glycaemia." (PMID 32824505, 2020). "The relative ratios of adiponectin/TNF-α, adiponectin/IL-1β, adiponectin/IL-10, TNF-α/IL-10 and IL-1β/IL-10 have been shown to be strongly correlated with the insulin resistance/sensitivity indexes (HOMA-IR and QUICKI)." (PMID 29785210, 2018). "Simultaneously, circulating levels of IL-10 and anti-inflammatory monocytes Mon-CD11c−CD206+ were also significantly diminished in patients with insulin resistance." (PMID 29675435, 2018). "Depletion of B-cell-specific IL-10 deteriorated adipose tissue inflammation and insulin resistance in DIO mice, whereas adoptive transfusion of adipose tissue IL-10-producing regulatory B cells improved those effects." (PMID 28491871, 2017). "Although IL-10 prevents HFD-induced insulin resistance, the effect of HFD on TNF-α and IL-10 in the heart is unclear." (PMID 25954207, 2015). "Blood samples were obtained for estimation of total cholesterol and triglycerides, insulin, glucose, insulin resistance, tumor necrosis factor alpha (TNF-α), interleukin 12 (IL12), and interleukin 10 (IL-10)." (PMID 25944984, 2015).
Insulin resistance (continued). "IL10 plays a critical role in limiting inflammation and a switch in anti- and pro-inflammatory balance towards pro-inflammatory state in overweight and obese adolescents may promote the progression of normal glucose tolerance to insulin resistance in adulthood." (PMID 23941335, 2013). "Out of the insulin-resistance mediating factors, plasminogen activator inhibitor-1 (PAI-1), MCP-1, IL-6, IL-8, IL-10 and tumour necrosis factor (TNF)-α were significantly elevated in these patients." (PMID 21470423, 2011). "Here, we further demonstrated that the injection of IL-10-treated SVFs into the adipose tissue of Leprdb/db mice decreased proinflammatory cytokine expression, suppressed plasma DPP4 activity, and ameliorated insulin resistance." (PMID 39125659, 2024). "By contrast, IL-10, which is produced by M2 ATMs, alleviates TNF-α-induced insulin resistance." (PMID 39303983, 2024). "G. gardneriana did not protect against insulin resistance, and caused in an increase in monocyte chemoattractant protein-1 (MCP-1) concentrations and a reduction in interleukin 10 (IL-10)." (PMID 36986038, 2023). "Insulin resistance in metabolic syndrome may result from the high secretion of TNF-α and the low secretion of IL-10." (PMID 38202328, 2023). "We found that JAZF‐1 and PPAR‐γ could promote Tregs differentiation and regulate insulin resistance by synergistically decreasing the expression levels of TNF‐α, IL‐1β and IL‐6 and increasing those of IL‐10 and TGF‐β." (PMID 36734198, 2023). "In particular, IL10-MSCs treated mice had a more decrease in insulin resistance compared with MSCs treated mice, similar to NCD mice, indicating IL10-MSCs could significantly improve insulin sensitivity in HFD mice, close to basal level." (PMID 35715850, 2022). "Multiple MSCs, especially IL10-MSCs transplantations, could counteract the adverse effects of HFD on body weight, adipose tissue inflammation, lipid metabolism, and systemic insulin resistance in mice." (PMID 35715850, 2022). "The low IL-10 level is negatively related to excessive insulin resistance of GDM patients, indicating that low IL-10 may increase insulin resistance of GDM patients." (PMID 36615730, 2022). "These Bregs suppressed inflammation and insulin resistance as B cell-specific lack of IL-10 enhanced adipose tissue inflammation and insulin resistance in DIO mice." (PMID 35960996, 2022). "High IL-10 levels may also increase insulin sensitivity by ameliorating the inflammatory responses to TNF-α and IL-6, which contribute to insulin resistance in PCOS." (PMID 34233746, 2021). "Additionally, it can regulate the gut microbiota, increase IL-10, and reduce IL-6 and tumor necrosis factor-α (TNF-α), as well as liver injury, and further reduce insulin resistance and regulate lipid metabolism disorders." (PMID 34574191, 2021). "Chemerin levels were directly and strongly correlated with IL-10 (r = 0.41) and interleukin-4 (r = 0.50) and inversely correlated to insulin resistance index (r = −0.23) in GDM but not NGDM." (PMID 34007846, 2021). "Additionally, HF and HF+FO/D groups showed insulin resistance, adipocyte hypertrophy, increased lipolysis and secretion of TNF-α, resistin and IL-10 adipokines by ING and RP adipocytes, and adiponectin only by the HF+FO/D group in ING adipocytes." (PMID 33652751, 2021). "M1 macrophages induce an inflammatory and insulin resistance state through the inhibition of insulin signaling, indirectly produced by TNF-α, IL-6, and IL-1β, while M2 macrophages protect against insulin resistance by an IL-10-dependent mechanism." (PMID 34944461, 2021). "The decline of IL-10 and elevation of TNF-α and IL-6 are reported to be important regulators underlying insulin resistance and a slow nonhealing chronic wound process." (PMID 32879654, 2020).
Insulin resistance (continued). "In line with previous reports, we also identified a positive association of systemic IL-6 levels with insulin resistance, whereas other cytokines (IL-1ß, TNF, IL-10) did not correlate significantly." (PMID 33349270, 2020). "We also observed increased plasma levels of IL10, which has been shown to inhibit the effects of IL6 with regards to insulin resistance, and may have contributed to the improved insulin sensitivity." (PMID 31724300, 2019). "On the other side, decreased IL-10 has been related to elevated serum concentrations of TNF-α, increased proportion of Mon-CD11c+CD206− over the Mon-CD11c−CD206+ subpopulation, hyperglycemia, and higher levels of insulin resistance in obese subjects." (PMID 29675435, 2018). "Our observations of higher LPS, CRP, TNF-α/IL-10 ratio, and HOMA-IR values in the omnivorous group reinforce previous hypothesis that a saturated fat-enriched diet could induce inflammation and insulin resistance." (PMID 28814977, 2017). "High‐fat diets induce the expression of IL10, an anti‐inflammatory cytokine, and increase the number of alternative anti‐inflammatory M2 macrophages in EAT, although the increased ratio of M1‐to‐M2 macrophages ultimately induces insulin resistance." (PMID 26499876, 2016). "Of note, elevated levels of TNFα, IL-1β, IL-6 and IL-10 mRNA in MO with high insulin resistance degree were not statistically different from the levels found in T2D-MO." (PMID 23110196, 2012). "Possibly, the produced IL-10, but also CD163 and arginase in adipose tissue macrophages only play a paracrine role, thereby preventing adipose tissue injury from excess inflammation and insulin resistance." (PMID 22018099, 2011). "Based on these findings, we hypothesized that macrophage M1 < M2 polarization is related to the EPO-induced renoprotective effects in sucrose-induced insulin resistance model rats and found that EPO decreased the M1 marker TNFα and increased the M2 markers Arg1 and IL10 in the kidney." (PMID 40943240, 2025). "Furthermore, UC-MSCs overwhelmingly homed to the spleen, and the ability of UC-MSCs to elevate serum IL-10 levels and alleviate insulin resistance was impaired in the absence of the spleen." (PMID 35313972, 2022). "In addition, aging mice with muscle-specific overexpression of IL-10 show little evidence of muscle inflammation and insulin resistance." (PMID 32857156, 2021). "In addition, studies have shown that IL-10 produced by Treg cells in VAT not only inhibits the release of TNF-α-induced inflammatory cytokines and chemokines but also protects adipocytes from the effects of TNF-α-induced insulin resistance." (PMID 34515616, 2021). "Although IL10 has been reported to be protective against diet-induced insulin resistance, it has also been reported that IL10 does not improve hepatic or systemic insulin sensitivity in high fat feeding and therefore it does not protect against insulin resistance." (PMID 26229237, 2015). "Additionally, insulin resistance increases the M1 proinflammatory response of macrophages, even increasing the secretion of TNF-α and other cytokines that can worsen vascular function, and decreases the M2 anti-inflammatory response by reducing the synthesis of IL-10." (PMID 38542702, 2024). "The induction of IL-10 expression in the adipose tissue might promote Foxp3+ Treg expansion and suppress liver inflammatory cytokine expression and plasma DPP4 activity that may ultimately lead to mitigated insulin resistance and glucose intolerance in diabetic mice." (PMID 35883204, 2022). "The results in our study suggest that IL-10 might counteract the negative effects of adiposity-related cytokines, such as IL-6, on insulin sensitivity, which is corroborated by a study in mice where IL-10 co-treatment prevented IL-6 induced insulin resistance." (PMID 35135482, 2022).
Insulin resistance (continued). "Inflammatory mediators, such as pro-inflammatory cytokines (TNF-α, IL-1β, and IL-8) as well as anti-inflammatory cytokines (IL-10 and TGF-β), can induce insulin resistance without affecting lipid breakdown." (PMID 40231066, 2025). "The major finding of the present study was that neither CET nor SIT has any significant effect on serum levels of I-6, IL-10, CRP, WBC, and insulin resistance index." (PMID 23725447, 2013). "Furthermore, in the women with insulin resistance, intake of MOJ for 4 weeks reduced the plasma VCAM-1 levels (554.99 ± 15.63 to 545.31 ± 14.65 ng·mL−1, p = 0.039) but the plasma levels of ICAM-1, C-reactive protein, TNF-α, IL-6, and IL-10 were not significantly altered." (PMID 37469434, 2023).
glioma (224 papers, 2003 to 2026). A benign or malignant brain and spinal cord tumor that arises from glial cells (astrocytes, oligodendrocytes, ependymal cells). "IL-10 is overexpressed in high-grade gliomas, and tumor-associated macrophages (TAMs) are an important source of IL-10." (PMID 40507329, 2025). "Glioma-associated IL-10 upregulates the expression of PD-L1 on TAMs and peripheral monocytes, which can then bind to and stimulate PD-1 on TILs, leading to T cell anergy." (PMID 36768342, 2023). "Another study reported that the IL-10 rs1800869 GG genotype causes an increase in IL-10 production, suggesting that the mutant allele G has significantly protective associations against glioma." (PMID 36009467, 2022). "We also evaluated a possible correlation of sHLA-G with the level of immunoregulatory and anti-inflammatory cytokine IL-10, pro-inflammatory cytokine IL-6, and their ratio (IL-10/IL-6), and the association of sHLA-G with the survival of glioma patients." (PMID 35626255, 2022). "There is a large number of macrophages infiltration in the glioma microenvironment, which is associated with a variety of factors secreted by tumor cells, including IL-4, IL-6, IL-10, TGF-β, microRNAs, macrophage colony-stimulating factor (M-CSF), and CCL2." (PMID 36483052, 2022). "In conclusion, systemic delivery of αCD40 resulted in the expansion of CD11b-expressing B cells in the brain and spleen of glioma-bearing mice, which was associated with a systemic increase of IL-10." (PMID 34226552, 2021). "Many studies have reported that high levels of TGF-β, EGF, MMP-2, MMP-9 and IL-10, and low levels of IL-12 can be produced by M2 polarized glioma-associated microglia/macrophages to promotes invasion, proliferation, immune evasion and angiogenesis of glioma." (PMID 34446611, 2021). "IL-10 production by gliomas seems to polarise the tumour associated macrophages and microglia in the tumour microenvironment." (PMID 31973059, 2020). "Their results showed that the injection of MWCNTs increased the influx of macrophages into the glioma cells and caused an increase of the tumor cytokine level (IL-10) in time-dependent and dose-dependent manners." (PMID 30970690, 2017). "Ours was the first study to associate the IL-10 rs1800871 C/T genotype with improved survival in low-grade glioma patients." (PMID 27811370, 2016). "IL-10 gene polymorphisms have been associated with multiple cancers, such as gastric, breast, and non-small cell lung cancer, as well as gliomas." (PMID 27811370, 2016). "IL-10 SNP rs1800871 was associated with improved survival in low-grade glioma cases, while PRKDC SNP rs7003908 was correlated with poor prognosis in high-grade patients." (PMID 27811370, 2016). "Consistent with its immunosuppressive actions elsewhere in the body, glioma-associated IL-10 down-regulates MHC class II expression on monocytes and inhibits IFN-γ and TNF-α production by immune cells." (PMID 26217588, 2015). "IL-10 also upregulates checkpoint molecule B7-H1 (PD-L1) on both glioma-associated macrophages and circulating monocytes in peripheral blood." (PMID 26217588, 2015). "In addition, TLR-induced immunosuppressive cytokines (such as TGF-β, IL-10) released from glioma-associated myeloid cells have been shown to impair NK function." (PMID 41157253, 2025). "Additionally, macrophages associated with gliomas secrete IL-10 and Transforming Growth Factor-β (TGF-β), further dampening immune cell activity." (PMID 38809931, 2024). "Glioma cells that cause brain tumor produce immunosuppressive compounds such as transforming growth factor-β, prostaglandins E, and interleukin (IL)-10, which could make them capable of staying away from the host’s immune system." (PMID 37799472, 2023). "Furthermore, triptolide promoted IL-2 secretion and reversed IL-10 inhibition caused by glioma cells." (PMID 37375698, 2023).